TPST1 (tyrosylprotein sulfotransferase 1)
Description:
Catalyzes the O-sulfation of tyrosine residues within acidic motifs of polypeptides, using 3'-phosphoadenylyl sulfate (PAPS) as cosubstrate.
Synonyms: TANGO13A
Tractability: Small molecule: a structure with a bound ligand is known. Antibody: UniProt predicts a signal peptide or a membrane-spanning region. PROTAC: its protein half-life has been measured.
Gene: Protein-coding gene on chromosome 7 (66,205,289 to 66,420,549, forward strand). Ensembl gene ENSG00000169902.
Subcellular location: Golgi apparatus membrane
Subcellular location (Human Protein Atlas): Golgi apparatus
Pathways (Reactome):
Disease: Defective F8 sulfation at Y1699
Metabolism: Cytosolic sulfonation of small molecules
Metabolism of proteins: Gamma carboxylation, hypusinylation, hydroxylation, and arylsulfatase activation
Gene Ontology:
Molecular function: protein homodimerization activity; protein-tyrosine sulfotransferase activity
Biological process: post-translational protein modification; 3'-phosphoadenosine 5'-phosphosulfate metabolic process; peptidyl-tyrosine sulfation
Cellular component: Golgi apparatus; Golgi membrane; membrane
Genetic constraint (gnomAD): Loss-of-function variants: 20 observed, 34.99 expected, observed/expected ratio (o/e) 0.57, 90% interval 0.4 to 0.83. The upper end of that interval is the gene's LOEUF score, 0.83, which puts it in group 3 of 6, group 1 being the genes least tolerant of losing a copy. Missense variants: 353 observed, 468.89 expected, observed/expected ratio (o/e) 0.75, 90% interval 0.69 to 0.82. Synonymous variants: 152 observed, 162.26 expected, observed/expected ratio (o/e) 0.94, 90% interval 0.82 to 1.07.
Homologues: Orthologues: chimpanzee TPST1 (100% identical), macaque TPST1 (98% identical), pig TPST1 (97% identical), dog TPST1 (97% identical), mouse Tpst1 (96% identical), chimpanzee TPST1 (95% identical), rat Tpst1 (95% identical), guinea pig TPST1 (95% identical), rabbit TPST1 (94% identical), tropical clawed frog tpst1 (88% identical), zebrafish tpst1 (78% identical), Drosophila melanogaster Tpst (58% identical), and 2 more. Paralogues in human: TPST2 (65% identical).
Diseases named in the same sentence as TPST1 in open-access papers:
TPST1 is named in the same sentence as 33 diseases in open-access papers, as found by Europe PMC text mining. Sharing a sentence is not in itself a finding about the gene and the disease. The quoted sentences say what the papers report.
nasopharyngeal carcinoma (4 papers, 2013 to 2023). A carcinoma arising from the nasopharyngeal epithelium. "It has been reported that TPST1 is overexpressed in bladder cancer, oral squamous cell cancer, breast cancer and barretina sarcoma and involved in the invasion and metastasis of head and neck carcinoma and nasopharyngeal carcinoma." (PMID 31333338, 2019). "Previous studies suggested that TPST1 upregulated expression levels in BLCA, breast cancer, tongue squamous cell carcinoma, and nasopharyngeal carcinoma and has a significant impact on the invasion and metastasis of hypopharyngeal cancer and colorectal cancer." (PMID 36814419, 2023). "Previous studies revealed that TPST1 could sulfate the tyrosine of C-X-C motif chemokine receptor (CXCR4) and the tyrosine sulfation might contribute to nasopharyngeal carcinoma metastasis." (PMID 30662454, 2018).
breast carcinoma (3 papers, 2019 to 2023). "A previous study reported that TPST1 is highly expressed in breast carcinoma, oral squamous cell carcinoma, and soft tissue sarcoma." (PMID 35281080, 2022).
atherosclerosis (2 papers, 2021 to 2023). A disease characterized by the build-up of fatty material and calcium deposition in the arterial wall resulting in partial or complete occlusion of the arterial lumen. "Knockout of TPST1 and TPST2 decreased atherosclerosis and peritoneal macrophage adherence and migration in CKD condition." (PMID 37424015, 2023).
glioma (2 papers, 2018 to 2026). A benign or malignant brain and spinal cord tumor that arises from glial cells (astrocytes, oligodendrocytes, ependymal cells). "Among these, TPST1 was associated with immunotherapy resistance and was upregulated in high-grade glioma." (PMID 41838327, 2026).
allergic asthma (1 paper, 2025). A asthma with a basis in a pathological type I hypersensitivity reaction. "This study suggests that obese patients defined by BMI may promote the development of allergic asthma by influencing the expression of plasma proteins such as TPST1, ROR1, and DAPK1." (PMID 39893495, 2025). "Furthermore, some of these plasma proteins, including TPST1, could potentially serve as therapeutic targets for treating allergic asthma in these patients." (PMID 39893495, 2025). "The results of this study indicate that plasma proteins such as TPST1, ROR1, and DAPK1 may mediate the relationship between obesity and allergic asthma." (PMID 39893495, 2025).
allergies (1 paper, 2020). "The gene TPST1 showed the largest Log2FC value of −2.7 with a p-value = 0.026 in DCs from patients with allergies." (PMID 33207814, 2020).
aortic atherosclerosis (1 paper, 2023). A atherosclerosis that involves the aorta. "Independent of kidney injury, we found that loss of TPST1 and TPST2 decreased aortic atherosclerosis in ApoE−/− mice." (PMID 37424015, 2023).
asthma (1 paper, 2025). "Additionally, sterol sulfate has been found to alleviate insulin resistance and systemic inflammation in obese mice, suggesting that TPST1 may also influence obesity-related asthma." (PMID 39893495, 2025).
autoimmune disease (1 paper, 2024). A disorder resulting from loss of function or tissue destruction of an organ or multiple organs, arising from humoral or cellular immune responses of the individual to their own tissue constituents. "Others were associated with autoimmune disease, such as systemic lupus erythematosus (SLE), ALS, and RA: CHIT1, IL18RAP, PHF24, and TPST1." (PMID 38978787, 2024).
COVID-19 (1 paper, 2024). A disease caused by infection with severe acute respiratory syndrome coronavirus 2. "Only two genes (TPST1 and NEBL2) fulfilled this criterion, and only one (TPST1) considering both COVID-19 datasets." (PMID 38302132, 2024).
depression (1 paper, 2022). "Finally, we identified ARG1, TPST1 and F5 as core genes associated with S100A12 expression in depression." (PMID 36325528, 2022). "The functional analysis of gene modules related to S100A12 also indicated that it may be involved in the immune regulatory response in depression, and the core genes of ARG1, TPST1 and F5 related to its expression were found." (PMID 36325528, 2022).
fibrosarcoma (1 paper, 2018). A malignant mesenchymal fibroblastic neoplasm affecting the soft tissue and bone. "By screening the Published Kinase Inhibitor Set, we identified oxindole-based inhibitors of the Ser/Thr kinase RAF (rapidly accelerated fibrosarcoma) as low-micromolar inhibitors of TPST1 and TPST2." (PMID 29934490, 2018).
pancreatic adenocarcinoma (1 paper, 2024). "The analyses demonstrated that the SNPs rs3757417 T>G and rs12373 A>C in the 3′-UTR of Tyrosylprotein Sulfotransferase 1 (TPST1) and pancreatic adenocarcinoma upregulated factor (PAUF), respectively, are considered potential prognostic markers for patients undergoing surgical resection." (PMID 39684686, 2024).
Primary hypothyroidism (1 paper, 2013). A type of hypothyroidism that results from a defect in the thyroid gland. "In a previous study we showed that Tpst2-/- mice had mild-moderate primary hypothyroidism, whereas Tpst1-/- mice were euthyroid." (PMID 23951251, 2013). "We reported that Tpst2-/- mice have mild-moderate primary hypothyroidism, whereas Tpst1-/- mice are euthyroid." (PMID 23951251, 2013). "In the Tpst2 knockout, we find both male sterility and primary hypothyroidism, but only very subtle changes in the Tpst1-/- knockout." (PMID 23951251, 2013). "We previously reported that Tpst2-/- mice on a 129S6 genetic background have mild-moderate primary hypothyroidism, whereas Tpst1-/- mice are euthyroid." (PMID 23951251, 2013). "Tpst2-/- mice have mild-moderate primary hypothyroidism, whereas Tpst1-/- mice are euthyroid." (PMID 23951251, 2013). "Our studies demonstrate that Tpst2-/-, but not Tpst1-/- mice, have salivary gland hypofunction and that salivary gland hypofunction is due solely to primary hypothyroidism." (PMID 23951251, 2013).
rheumatoid arthritis (1 paper, 2022). A chronic, systemic autoimmune disorder characterized by inflammation in the synovial membranes and articular surfaces. "TPST1 is up-regulated in bone marrow-derived monocytes from patients with rheumatoid arthritis, which is related to the immune response." (PMID 35204186, 2022).
urothelial bladder cancer (1 paper, 2022). "TPST1 up-regulation is related to high pathological staging and low survival rate in patients with urothelial bladder cancer and a decreased level of tissue factor pathway inhibitor (TFPI)." (PMID 35204186, 2022).
tumor (6 papers, 2013 to 2026). "TPST1-high tumor cells exhibited proliferative enrichment and potential interaction with myeloid cells via PTN-NCL and EREG/AREG-EGFR signaling pathways." (PMID 41838327, 2026). "Further investigation found that the elevated TPST1 or P3H4 expression were significantly associated with poor survival and high tumor pathological stage." (PMID 31333338, 2019). "The studies in cell culture models suggested that induction of TPST-1 expression by LMP1 contributes to tumor cell invasion and metastasis." (PMID 23472069, 2013). "In tumour tissues, TPST1 appears to be significantly lower expression than in control lung tissues." (PMID 32742772, 2020). "Of the 16 metabolism-related genes, we found that AOC2, IDUA, GPC2, CSPG4, TPST1, and CYP1B1 were differentially expressed between tumor and normal tissue at the protein level according to the Human Protein Atlas (HPA) cohort." (PMID 35281080, 2022). "Of the 16 metabolism-related genes, we found AOC2, IDUA, GPC2, CSPG4, TPST1, and CYP1B1 to be differentially expressed between tumor and normal tissues at the protein level." (PMID 35281080, 2022). "The TPST-1 protein was detected mainly in the cytoplasm and the LMP1 protein was detected in both the membranes and cytoplasm of the tumor cells." (PMID 23472069, 2013). "The results indicate that the TPST-1 protein was detected in tumor cells in 1of 6 nonmetastatic human NPC tissues and in 29 of 40 lymph node metastases." (PMID 23472069, 2013).
cancer (3 papers, 2013 to 2023). A tumor composed of atypical neoplastic, often pleomorphic cells that invade other tissues. "A CXCR4 peptide can be modified at position 21 by expression of TPST-1, but the mechanisms of TPST-1 activation and function in cancer remain enigmatic." (PMID 23472069, 2013). "Studies depicting the function of tyrosylprotein sulfotransferase 1 (TPST1) in cancer are rare." (PMID 32742772, 2020). "However, the mechanism explaining how TPST-1 can be regulated by LMP1 in cancer progression is a key question yet to be answered and remains quite obscure." (PMID 23472069, 2013). "It is interesting to note that latent membrane protein 1 (LMP1), which is encoded by EBV, induces tyrosine sulfation of CXCR4 through upregulation of tyrosylprotein sulfotransferase-1 (TPST-1) and promotes metastasis of cancer cells, a mechanism that could also be applied to GPR15." (PMID 37457732, 2023).
TPST1 also shares sentences with these, for which no sentence is quoted: bladder cancer (2 papers); oral squamous cell carcinoma (2); cognitive decline (1); colorectal cancer (1); head and neck carcinoma (1); hypopharyngeal cancer (1); Insulin resistance (1); lung carcinoma (1); lymph node metastasis (1); Obesity (1); Plasmodium vivax malaria (1); prostate carcinoma (1); soft tissue sarcoma (1); systemic lupus erythematosus (1); tongue squamous cell carcinoma (1).